WRAP53 (WD repeat containing antisense to TP53)
Diseases named in the same sentence as WRAP53 in open-access papers (continued):
Sharing a sentence is not in itself a finding about the gene and the disease.
head and neck squamous cell carcinoma (2 papers, 2014 to 2023). A squamous cell carcinoma that arises from any of the following anatomic sites: lip and oral cavity, nasal cavity, paranasal sinuses, pharynx, larynx, and salivary glands. "Investigations with samples from patients with head and neck squamous cell carcinoma showed that WRAP53 levels are higher in patients with recurrent tumors compared with patients with positive cancer outcomes." (PMID 24626331, 2014).
hepatocellular carcinoma (2 papers, 2022 to 2023). A malignant tumor that arises from hepatocytes. "LncRNA MFI2-AS1 is in clinical trials for use as a diagnostic biomarker for kidney cancer, and lncRNAs UCA1 and WRAP53 are in clinical trials for use as diagnostic biomarkers for hepatocellular carcinoma." (PMID 37891744, 2023).
lymph node metastasis (2 papers, 2012 to 2014). "Overexpression of WRAP53 was significantly correlated with tumor infiltration depth (P = 0.000), clinical stage (P = 0.001), and lymph node metastasis (P = 0.025)." (PMID 24626331, 2014). "We also observed that overexpression of WRAP53 is significantly correlated with lymph node metastasis and TNM stage." (PMID 24626331, 2014). "Overexpression of WRAP53 correlated with tumor infiltration depth, clinical stage, and lymph node metastasis." (PMID 24626331, 2014).
ovarian tumors (2 papers, 2021 to 2023). "Mutations in WRAP53 gene results in shortening telomeres and reduced expression in ovarian tumors has been correlated with attenuated DNA damage response, since the protein WRAP53β rapidly accumulates at DNA breaks and recruits DNA repair proteins." (PMID 37299586, 2023).
rectal tumor (2 papers, 2012 to 2015). "Previously, the WRAP53 protein has been reported to be overexpressed in a broad range of cancer cell lines compared to non transformed cells, as well as in primary rectal tumor cells compared to normal mucosal cells." (PMID 26460974, 2015). "Thus, the primary rectal tumors show enhanced the WRAP53 expression compared to normal mucosa independently of radiotherapy." (PMID 22805008, 2012). "Thus, the WRAP53 is overexpressed in primary rectal tumor compared to normal mucosa." (PMID 22805008, 2012).
spinal muscular atrophy (2 papers, 2010 to 2014). A motor neuron disease that affect the muscles, and characterized by muscle weakness and atrophy resulting from progressive degeneration and irreversible loss of the anterior horn cells in the spinal cord (i.e., lower motor neurons) and the brain stem nuclei. "Finally, we report deficient WRAP53–SMN binding in patients with spinal muscular atrophy, suggesting a role in this pathology." (PMID 21072240, 2010). "Other proteins enriched in the CB are the survival of motor neuron (SMN) protein, which is mutated in most cases of spinal muscular atrophy, and WRAP53 (also known as TCAB1 or WDR79), which plays a pivotal role in RNP biogenesis." (PMID 24659245, 2014).
Alzheimer disease (1 paper, 2015). A progressive, neurodegenerative disease characterized by loss of function and death of nerve cells in several areas of the brain leading to loss of cognitive function such as memory and language.
colon cancer (1 paper, 2012). "Moreover, WRAP53 positive colon cancer cells underwent spontaneous apoptosis upon reduction of WRAP53 expression." (PMID 22805008, 2012).
craniometadiaphyseal dysplasia (1 paper, 2021). "Our study showed that craniometadiaphyseal dysplasia was caused by a deficiency of WRAP53 with autosomal recessive inheritance." (PMID 34484289, 2021). "Therefore, we show for the first time that biallelic frameshift deletion mutations in WRAP53 result in craniometadiaphyseal dysplasia." (PMID 34484289, 2021).
gastric cancer (1 paper, 2025). A primary or metastatic malignant neoplasm involving the stomach. "For example, ALKBH5 is downregulated in gastric cancer and inhibits gastric cancer metastasis by inhibiting WRAP53 translation in a m6A-dependent manner." (PMID 40774945, 2025).
metastatic tumors (1 paper, 2012). "In WRAP53 negative group of either primary or metastatic tumors, radiotherapy had no prognostic effect (p > 0.05, data not shown)." (PMID 22805008, 2012). "The WRAP53 expression was not statistically different between primary and metastatic tumor." (PMID 22805008, 2012).
Nail dystrophy (1 paper, 2021). Onychodystrophy (nail dystrophy) refers to nail changes apart from changes of the color (nail dyschromia) and involves partial or complete disruption of the various keratinous layers of the nail plate. "Here, we reported a case of a patient also with compound heterozygous mutations in the WRAP53 gene, and this patient presented with one of the classic DC symptoms—nail dystrophy, which is one of the diagnostic cutaneous triad for DC." (PMID 34484289, 2021).
Sepsis (1 paper, 2025). Sepsis is defined as life-threatening organ dysfunction caused by a dysregulated host response to infection. "In the present research, several genes linked to ER stress-response genes were identified, including PRDM16, WRAP53, LTF, and VLDLR, which exhibited increased expression in sepsis." (PMID 40867920, 2025). "In septic foals, several genes, including PRDM16, WRAP53, LTF, and VLDLR, were activated to address inflammation or enhance survival rates in sepsis." (PMID 40867920, 2025).
urinary bladder cancer (1 paper, 2018). A primary or metastatic malignant neoplasm involving the bladder. "The predictive results derived from our method inferred that ncRNAs H19 and WRAP53 might be associated with urinary bladder cancer." (PMID 29671405, 2018).
cancer (39 papers, 2010 to 2025). A tumor composed of atypical neoplastic, often pleomorphic cells that invade other tissues. "Loss of WRAP53 in this situation allows the escape of damaged cancer cells and the formation of even more malignant clones." (PMID 36975842, 2023). "Genetic alterations such as mutations or deletions involving WRAP53 are present in several types of cancer (cBioPortal, accessed on 12 August 2022)." (PMID 36354684, 2022). "WRAP53 protein is implicated in telomere elongation caused by telomerase and is highly expressed in a cancer cell." (PMID 30405890, 2018). "Moreover, it appears like loss of WRAP53 in later stages of tumor evolution leads to the inactivation of the DNA damage response, survival of the genetically unstable tumor cell, and cancer progression." (PMID 36975842, 2023). "In this review, we seek to discuss the cellular roles of WRAP53, its possible pathways in carcinogenesis as an oncogene, and a molecular biomarker to be investigated in cancer prognoses." (PMID 36354684, 2022). "Currently, the overexpression of WRAP53 transcripts has been pointed out as a biomarker for a large cohort of cancer subtypes, such as colorectal, hepatocellular, head and neck, breast, ovarian, and esophageal squamous cell cancers." (PMID 36354684, 2022). "A role of WRAP53 in cancer is further supported by observations of elevated levels of the protein in human cancer cells compared to normal cells." (PMID 26460974, 2015). "Mahmoudi and colleagues recently demonstrated that WRAP53 protein is overexpressed in many different cancer cell lines, and that WRAP53 overexpression promotes cellular transformation." (PMID 24626331, 2014). "The WRAP53 overexpression promotes cellular transformation, whereas WRAP53 knockdown triggers apoptosis of cancer cells." (PMID 22805008, 2012). "We identified 42 germline variants of interest in 58 of 9089 TCGA participants (0.6%) across all cancer entities, including 8 variants present in the NCI’s TBD cohort (4 loss of function and 4 missense affecting either CTC1, RTEL1, TERT, or WRAP53) (eTable 5 and eTable 15 in Supplement 1)." (PMID 39661387, 2024). "Thus, the cancer cell is potentially dependent on an upregulated DNA damage response before WRAP53 expression is lost." (PMID 36975842, 2023). "In our study several interesting genes were upregulated in GFP+ alone including MAGI2, SALL4, and WRAP53, most which had been implicated in human cancers and with no known role in alphaviral infection or disease." (PMID 36680176, 2022).
cancer (continued). "Likewise, miR-302a expression was more frequent in the cancers with necrosis (P = 0.033) and strong WRAP53 expression (P = 0.015)." (PMID 33123477, 2020). "NATs play key roles in carcinogenesis, and although WRAP53 is known to increase cancer cell survival, its role in ESCC clinicopathology is unknown." (PMID 24626331, 2014). "The WRAP53 gene has been shown to be involved in the development of primary human cancer." (PMID 24626331, 2014). "The following studies indicated that WRAP53 promoted cancer cell survival and depletion of WRAP53 using exogenous shRNA induces apoptosis in vitro, and also WRAP53 is necessary to form Cajal bodies and can direct the survival of motor neuron complex to Cajal bodies." (PMID 25070141, 2014). "We especially focused our discussion on showing the different roles of WRAP53 in cell biology, showing that structural alterations or alterations in its expression levels can lead to a tumorigenesis process while, on the other hand, its regulation proves to be beneficial in cancer prognosis." (PMID 36354684, 2022). "However, more clinical and experimental investigations are still needed for a better understanding of the role of WRAP53 and its transcripts in the mechanisms involved in tumorigenesis so that it may be addressed as potential new biomarker in cancer and a target in the development of new treatments." (PMID 36354684, 2022). "Genes involved in cancer progression were also readily identified (as outlined for ATM and MXI above), and these also included WRAP53 as AS." (PMID 23383294, 2013). "Reassuringly, individuals harboring a heterozygous variant in a predominately AR gene, CTC1 or WRAP53, and including DKC1 (females), were not at increased risk of cancer." (PMID 39661387, 2024). "WRAP53 modulation can modulate cancer radiosensitivity because of the negative correlation which exists between WRAP53 and cancer cells radiosensitivity." (PMID 30405890, 2018). "WRAP53 knockdown through RNA interference was shown to trigger apoptosis in cancer cells but not in normal human fibroblasts, implying that WRAP53 expression is important for cancer cell survival." (PMID 26460974, 2015). "Like SMN and WRAP53, the expression of coilin is also increased in transformed cells compared to primary cells, further indicating that coilin is part of the upregulated RNP biogenesis machinery present in cancer cells." (PMID 24659245, 2014). "WRAP53 protein has been found overexpressed in a broad range of human cancer cell lines in comparison to non-transformed cells." (PMID 22805008, 2012). "It has been hypothesized that this increased expression is a natural response to the accumulating amounts of DNA damage known to occur in cancer cells rather than WRAP53 having oncogenic properties." (PMID 36975842, 2023). "Thus, little evidence for an enrichment of low WRAP53 levels in locally recurrent cancer after radiotherapy was found." (PMID 36975842, 2023).
tumor (24 papers, 2012 to 2025). "The co-purification of dyskerin complexes from tumor cell lines allowed the detection of the protein TCAB1 (also known as WDR79 or WRAP53), which is associated with telomerase." (PMID 36902458, 2023). "Loss of WRAP53 activity is then favorable for the tumor cell and likely reflects the survival of DNA repair‐deficient and genetically unstable cells that upon clonal expansion drives tumor progression." (PMID 36975842, 2023). "Low levels of WRAP53 protein, according to C1‐antibody, were associated with factors indicating worse prognosis (larger tumor size, higher TNM stage, higher frequency of HER2‐positive and triple‐negative subtype, and histologic grade III)." (PMID 36975842, 2023). "The association of WRAP53 with some clinicopathological variables (tumor size, node status and grade) was observed only in the validation set." (PMID 26460974, 2015). "In the validation set, an association between WRAP53 and tumor size, node status and grade was observed." (PMID 26460974, 2015). "Furthermore, there is strong evidence that several of the candidate genes are unlikely to be genuine HGSOC predisposition genes (even when highly ranked for LoF variant enrichment in cases versus controls), since the variant allele is lost in one or more tumours (e.g. WRAP53)." (PMID 39794353, 2025). "Cajal bodies organize snRNP biogenesis and telomerase trafficking through the scaffold protein WRAP53, also called TCAB1, and alterations in this pathway rewire RNA maturation and DNA maintenance processes central to tumor biology." (PMID 41191214, 2025). "WRAP53 is overexpressed in diverse tumor cell lines and clinical materials, promotes cellular transformation, and protects cancer cells through its roles in Cajal body integrity, SMN complex trafficking, and telomerase localization." (PMID 41191214, 2025). "Due to its participation in several complex cellular processes, WRAP53 seems to act both as a tumor suppressor and as an oncogene." (PMID 36354684, 2022). "In short, high levels of WRAP53 transcripts were observed to be present in a variety of tumor cell lines." (PMID 36354684, 2022). "The expression of WRAP53 protein was negatively correlated with the degree of tumor differentiation (P = 0.133)." (PMID 24626331, 2014). "On the other hand, WRAP53 expression was positively correlated with the depth of tumor invasion (P = 0.000) and lymph node metastasis (P = 0.025)." (PMID 24626331, 2014). "The IHC results showed that, in general, WRAP53 was predominantly expressed in the nuclei of tumor cells, especially in immature tumor cells and progenitor cells in the basal and/or suprabasal layer." (PMID 24626331, 2014). "Our study of the tissues of 134 ESCC patients showed that increased WRAP53 protein expression correlates with increased depth of tumor invasion and that WRAP53 expression is significantly higher in T III and T IV ESCC tissues than in TI and T II ESCC tissues." (PMID 24626331, 2014). "Patient and tumor characteristics in relation to nuclear WRAP53 protein levels (C1‐antibody)." (PMID 36975842, 2023). "Thus, WRAP53 overexpression is related not only to carcinogenesis onset but also tumor development and progression, which leads to being pointed out as an oncogene." (PMID 36354684, 2022). "WRAP53 transcripts may also be translated into WRAP53 protein, supporting the proliferation of progenitor cells and tumor cells by binding to telomerase to add telomere repeats to chromosome ends." (PMID 24626331, 2014). "However, the role of WRAP53 in tumor development and progression remains largely unclear, and its correlation with clinical significance remains to be elucidated." (PMID 24626331, 2014). "Moreover, we investigated whether radiotherapy treatment led to the enrichment of tumor cells with low levels of WRAP53 protein in the subsequent local recurrence, compared with the paired primary tumor." (PMID 36975842, 2023).
tumor (continued). "WRAP 53 staining was also observed in the nuclei of cells undergoing pathological mitosis and fully keratinized tumor cells in keratin pearls showed inconspicuous or absent WRAP53 immunoreactivity." (PMID 24626331, 2014). "In the non-radiotherapy group, WRAP53 expression was significantly increased from the distant (p = 0.03) or adjacent mucosa (p = 0.03) to the primary tumor." (PMID 22805008, 2012). "Additionally, WRAP53 was overexpressed in the IDH-mutant tumors, suggesting that the tumor cells may achieve immortality by telomere lengthening." (PMID 38254737, 2024). "Wrap53 expression was not correlated with age, gender, or tumor differentiation." (PMID 24626331, 2014). "Its gene product, WRAP53 (telomerase Cajal body protein, TCAB1) specifically interacts with TERT (AS on PI3K ablation) and essentially regulates telomerase trafficking, Cajal body formation and telomerase function and is thus of key importance for survival of particularly tumor cells." (PMID 23383294, 2013).
WRAP53 also shares sentences with these, for which no sentence is quoted: infection (2 papers); lung adenocarcinoma (2); nasopharyngeal carcinoma (2); acute lymphoblastic leukemia (1); acute myeloid leukemia (1); blood cancer (1); cholangiocarcinoma (1); Dubowitz syndrome (1); giant cell lung carcinoma (1); hematological malignancies (1); Infertility (1); kidney cancer (1); neurodevelopmental disorder (1); pancreatic ductal adenocarcinoma (1); squamous cell carcinoma (1); squamous cell lung carcinoma (1); thyroid tumours (1).